CREB5 (cAMP responsive element binding protein 5)
Description:
Binds to the cAMP response element and activates transcription.
Synonyms: CREB-5; CRE-BPa; CREBPA; H_GS165L15.1
Tractability: Antibody: the Human Protein Atlas places it where antibodies can reach. PROTAC: UniProt records ubiquitination sites on it; ubiquitination databases record sites on it.
Gene: Protein-coding gene on chromosome 7 (28,299,321 to 28,825,894, forward strand). Ensembl gene ENSG00000146592.
Subcellular location: Nucleus
Subcellular location (Human Protein Atlas): Nucleoplasm; Nuclear bodies; Plasma membrane; Vesicles
Gene Ontology:
Molecular function: DNA-binding transcription factor activity; protein binding; sequence-specific double-stranded DNA binding; cAMP response element binding; DNA-binding transcription factor activity, RNA polymerase II-specific
Biological process: positive regulation of DNA-templated transcription; regulation of transcription by RNA polymerase II; regulation of DNA-templated transcription
Cellular component: extracellular exosome; chromatin; nucleus
Genetic constraint (gnomAD): Loss-of-function variants: 14 observed, 51.95 expected, observed/expected ratio (o/e) 0.27, 90% interval 0.18 to 0.42. The upper end of that interval is the gene's LOEUF score, 0.42, which puts it in group 1 of 6, group 1 being the genes least tolerant of losing a copy. Missense variants: 571 observed, 691.73 expected, observed/expected ratio (o/e) 0.83, 90% interval 0.77 to 0.88. Synonymous variants: 236 observed, 246.97 expected, observed/expected ratio (o/e) 0.96, 90% interval 0.86 to 1.06.
Homologues: Orthologues: macaque CREB5 (99% identical), chimpanzee CREB5 (99% identical), rat Creb5 (98% identical), mouse Creb5 (97% identical), pig CREB5 (97% identical), rabbit CREB5 (96% identical), tropical clawed frog creb5 (88% identical), dog CREB5 (88% identical), guinea pig CREB5 (87% identical), zebrafish creb5a (44% identical), Caenorhabditis elegans atf-7 (18% identical). Paralogues in human: ATF7 (44% identical), ATF2 (42% identical).
Diseases named in the same sentence as CREB5 in open-access papers:
CREB5 is named in the same sentence as 80 diseases in open-access papers, as found by Europe PMC text mining. Sharing a sentence is not in itself a finding about the gene and the disease. The quoted sentences say what the papers report.
colorectal cancer (18 papers, 2019 to 2025). A primary or metastatic malignant neoplasm that affects the colon or rectum. "CREB5 gene affects the survival of patients by regulating colorectal cancer metastasis-associated signaling pathways." (PMID 34143809, 2021). "Overexpression of CREB5 enhanced the invasiveness and metastatic potential of colorectal cancer cells, whereas silencing CREB5 decreased these capabilities." (PMID 40862718, 2025). "CREB5 directly activates mesenchymal-epithelial transition to promote the invasiveness and metastasis of colorectal cancer and regulates vasculogenic mimicry in breast cancer cells." (PMID 38191389, 2024). "Previous studies have demonstrated that miR-132-3p regulates cell proliferation, metastasis, and migration in colorectal cancer (CRC) by interacting with CREB5." (PMID 38637796, 2024). "The miRNA miR-3913-5p inhibits colorectal cancer cell proliferation, migration and invasion, in concert with its regulation of and by CREB5 and ATF2." (PMID 37816820, 2023). "And CREB5 is overexpressed in colorectal tumors and capable of enhancing proliferation, invasion and metastasis of colorectal cancer cells." (PMID 36890812, 2023). "It had been reported that CREB5 facilitated multiple tumors progression, such as colorectal cancer and prostate cancer." (PMID 36565037, 2023). "Previously, we found that CREB5 was involved in the occurrence and development of colorectal cancer (CRC) using bioinformatics analysis." (PMID 32843066, 2020). "LncRNA-SNHG5 has been found to promote the development of colorectal cancer by sponging miR-132-3p/CREB5." (PMID 32131767, 2020). "For example, SNHG5 affects cell proliferation, metastasis and migration of colorectal cancer through regulating miR-132-3p/CREB5 and SNHG20 promotes the tumorigenesis of oral squamous cell carcinoma via targeting miR-197/LIN28 axis." (PMID 30858762, 2019). "The ATF2/miR-3913-5p/CREB5 axis is considered a potential therapeutic target for colorectal cancer." (PMID 39633985, 2024). "Although the detailed function of CREB5 has yet to be clarified, it has been reported that CREB5 is highly expressed in several cancers, such as colorectal cancer, epithelial ovarian cancer, and hepatocellular carcinoma, and involved in their metastasis, invasion, and proliferation." (PMID 39015025, 2024). "Interestingly, let-7a-5p was found to be downregulated in colorectal cancer, and let-7a-5p increased colorectal cancer cell apoptosis by regulating CREB5 and inhibited colon cancer cell proliferation, migration, and metastasis." (PMID 37966243, 2023). "Specifically, CREB5 has been shown to promote cell proliferation and correlate with a poor prognosis in hepatocellular carcinoma, while the lncRNA SNHG5 affects the cell proliferation, metastasis, and migration of colorectal cancer through regulating miR-132–3p/CREB5." (PMID 35754483, 2022). "Furthermore, previous studies reported miR-132-3p restrained growth and metastasis of colorectal cancer cells via decreasing Derlin-1 or cAMP responsive element binding protein 5 (CREB5)." (PMID 33685455, 2021). "However, examination of TCGA colorectal cancer datasets via cBioPortal revealed rare amplification of CREB5, suggesting that overexpression of CREB5 is controlled at transcriptional and post-transcriptional levels." (PMID 32843066, 2020). "Leong Pei predicted that miR-124-3 with a variant allele targets novel genes DCC (deleted in colorectal cancer) and CREB5 (cyclic AMP-responsive element-binding protein 5) rather than PTPN12 (as predicted by public databases)." (PMID 34925466, 2021).
prostate carcinoma (12 papers, 2010 to 2026). A carcinoma that arises from epithelial cells of the prostate gland. "CREB5 is associated with advanced PCa and was found to be overexpressed in metastatic castration-resistant prostate cancers promoting antiandrogen therapy resistance." (PMID 39337607, 2024). "In addition, the provirus integration site for xenotropic murine leukemia virus-related virus (XMRV), an infectious retrovirus associated with a predisposition for prostate cancer, has also been mapped to CREB5." (PMID 24376627, 2013). "In AR-positive prostate cancer cells, CREB5 interacts with and enhances FOXA1 and AR activity thereby regulating a subset of targets such as MYC and genes related to cell cycle, Wnt signaling and EMT." (PMID 38233872, 2024). "We observed that the elements in which CREB5 retained or gained sites were statistically significantly enriched of other nuclear proteins in which ChIP-seq had been performed in prostate cancer cell lines." (PMID 35550030, 2022). "When considering the subset of ARBs specific to progression, CREB5 indeed bound ARBs in prostate cancer (12.7%) or mCRPC (8.6%) tissue at higher rates as compared to normal prostate ARBs (0.2%)." (PMID 35550030, 2022). "To evaluate these findings, we collected mRNA from luciferase or CREB5-overexpressing prostate cancer cells, including the AR-dependent LNCaP and LAPC-4 cells, as well as the AR-negative PC3 and DU145 cells." (PMID 35550030, 2022). "Recently, overexpression or amplification of CREB5 was reported to promote proliferation and mediate resistance to AR inhibition in metastatic castration-resistant prostate cancers." (PMID 32843066, 2020). "In prostate cancers, CREB5 overexpression occurs through both copy number gain and increased gene expression." (PMID 32843066, 2020). "Experimental investigations showed that CREB5 was upregulated in ovarian cancers, hepatocellular carcinoma, and prostate cancer." (PMID 32843066, 2020). "CREB5 is a member of the cAMP-responsive element (CRE)-binding protein family implicated in tumorigenesis in acute myeloid leukemia and prostate cancer." (PMID 24376627, 2013). "CREB5 has also been noted to serve as an integration site for xenotropic murine leukemia virus-related virus (XMRV) in prostate cancer tissue from patients homozygous for a reduced activity variant of the antiviral enzyme RNase L." (PMID 20487506, 2010). "Consistent with the previous results, in the present study, we found that SE is regulated by ERS and induces EMT in HCC cells by affecting the transcription of the key target gene CREB5, which has been indicated as a stem cell-like factor in gliomas and prostate cancer." (PMID 39915455, 2025). "Meanwhile, CREB5 promotes enzalutamide resistance in prostate cancer." (PMID 38233872, 2024). "In addition, CREB5 was shown to be a modulator of androgen receptor signals in prostate cancer cells, which can promote enzalutamide resistance in vivo and in vitro." (PMID 35773668, 2022). "Moreover, overexpression or amplification of CREB5 promoted proliferation and mediated resistance to AR inhibition in metastatic castration-resistant prostate cancers." (PMID 32843066, 2020). "In prostate cancer, CREB5 could improve resistance to enzalutamide with the help of FOXA1 and selectively enhance the interaction of AR with target genes critical for survival." (PMID 32843066, 2020). "Furthermore, there are four related literatures on the PubMed website reporting the relationship between CREB5 and tumor resistance, of which only one paper preliminarily clarified the molecular mechanism of CREB5 promoting prostate cancer resistance to androgen receptor antagonists." (PMID 35773668, 2022). "In promoting proliferation in ART, CREB5 exhibited a strong degree of interaction with known AR transcription machinery, including FOXA1, HOXB13, and GRHL2, as well as novel prostate cancer regulators TBX3 and NFIC." (PMID 35550030, 2022).
prostate carcinoma (continued). "Together, we found TBX3 and NFIC were nuclear proteins associated with CREB5, FOXA1, and functionally impacted prostate cancer cell viability and ART resistance even absent of CREB5." (PMID 35550030, 2022).
breast carcinoma (7 papers, 2020 to 2025). "Additionally, BPS upregulates genes (THBS4, PPARGC1A, CREB5, COL5A3) related to breast cancer progression." (PMID 33330580, 2020). "Independent of CREB5 and FOXA1, TBX3 expression has been shown to be required for viability of breast cancer cells." (PMID 35550030, 2022).
hepatocellular carcinoma (6 papers, 2020 to 2025). A malignant tumor that arises from hepatocytes. "The elevated CREB5 promoted cellular proliferation in hepatocellular carcinoma, cell invasion in ovarian cancer, and resistance to androgen-receptor antagonists in prostate cancer." (PMID 37816820, 2023). "Consistent with our results, upregulation of CREB5 has been reported to be responsible for poorer outcomes in patients with epithelial ovarian cancer and hepatocellular carcinoma." (PMID 32843066, 2020). "High CREB5 expression correlated with a poor prognosis in epithelial ovarian cancer and hepatocellular carcinoma." (PMID 32843066, 2020). "The effects of CREB5 overexpression on promoting cell proliferation and migration have been demonstrated using in vitro assays in human hepatocellular carcinoma cells and CRC cell lines." (PMID 32843066, 2020). "CREB5 overexpression increased the proliferation of hepatocellular carcinoma." (PMID 32843066, 2020).
Insulin resistance (5 papers, 2017 to 2023). Increased resistance towards insulin, that is, diminished effectiveness of insulin in reducing blood glucose levels. "Key down-regulated genes (i.e., CREB5, SLC2A4, SREBF1, CYP1A1, CHARD and COMP) are related to insulin resistance, response to virus infection, AMPK signalling and ECM receptor interaction (Table A6)." (PMID 34830490, 2021).
ovarian carcinoma (4 papers, 2020 to 2023). A malignant neoplasm originating from the surface ovarian epithelium. "RNA-seq analysis of the CFP1-deleted ovarian cancer cells transcriptome showed that 703 genes were altered, and gene ontology analysis showed that many of these genes were associated with cell mitosis and cell cycle regulation, such as CREB5 and BST2." (PMID 35864225, 2022). "CREB5 overexpression has also been determined in fresh tissue and epithelial cell lines of ovarian cancer with a positive correlation between high CREB5 expression and tumor advancement stage." (PMID 36497095, 2022). "While the expression of NOG, S1PR1, BTG4, and CREB5 genes was significantly increased, that of RASSF9, DNMT1, BST2, and SETD1A genes was significantly decreased in CFP1-deleted A2780 and ES-2 ovarian cancer cells, based on qRT-PCR results." (PMID 35864225, 2022).
Parkinson disease (4 papers, 2015 to 2025). A progressive degenerative disorder of the central nervous system characterized by loss of dopamine producing neurons in the substantia nigra and the presence of Lewy bodies in the substantia nigra and locus coeruleus. "CREB5 has been implicated in Alzheimer's and Parkinson's diseases." (PMID 25705681, 2015). "The CREB5/CACNA1B/GNB4/PPP2R5A gene was found to be closely related to Parkinson’s disease in pathways of dopaminergic synapses." (PMID 37323142, 2023).
glioma (3 papers, 2023 to 2025). A benign or malignant brain and spinal cord tumor that arises from glial cells (astrocytes, oligodendrocytes, ependymal cells). "To validate the expression patterns of CREB5 in gliomas, we analyze the mRNA expression of CREB5 in glioma cell lines." (PMID 38418476, 2024). "Next, we analyzed the expression of CREB family genes according to glioma grade and observed that some genes, including CREB5, were highly expressed in grade IV GBM compared to grade II or III." (PMID 38418476, 2024). "In order to figure out the oncogene associated with glioma, we selected five genes to preform qRT-PCR experiments, including XPR1, QKI, CREB5, ACVR2B and ABL2." (PMID 37407973, 2023). "Moreover, in the classical GBM subtype, a correlation was confirmed between the CREB5 gene and genes important for stemness of glioma stem cells, such as OLIG2 and NES." (PMID 38418476, 2024). "We found that GSCs had considerably higher levels of CREB5 expression when compared to non-stem cell glioma cells and normal human astrocytes (NHA)." (PMID 38418476, 2024). "In addition, previous studies revealed that XPR1, ACVR2B and CREB5 could promote progression of diverse cancers, but they were not reported in glioma." (PMID 37407973, 2023).
Achalasia (2 papers, 2024). A disorder of esophageal motility characterized by the inability of the lower esophageal sphincter to relax during swallowing and by inadequate or lacking peristalsis in the lower half of the body of the esophagus. "Whole-exome sequencing (WES) on achalasia patients and controls revealed an association between the disease and common missense variants rs1705003 (CUTA) and rs1126511 (HLA-DPB1), and three rare variants (CREB5, ESYT3, and LPIN1) in an independent cohort." (PMID 38792545, 2024).
Cluster headache (2 papers, 2014 to 2025). A type of headache characterized by repeated attacks of unilateral pain lasting 15 to 180 minutes and associated with local autonomic signs. "PTPRB has been reported to be a drug addiction-associated gene, and CREB5 to be upregulated in the blood of cases with cluster headaches when compared to controls." (PMID 25105010, 2014).
COVID-19 (2 papers, 2022 to 2023). A disease caused by infection with severe acute respiratory syndrome coronavirus 2. "Finally, three genes associated with immunity (B4GALT5, CRISPLD2, F5) and two genes associated with ferroptosis (ACSL1, CREB5) were identified up-regulated in COVID-19-related IS." (PMID 37606960, 2023). "As a result of intersecting 73 COVID-19-related IS genes with ferroptosis genes, we obtained two ferroptosis genes (ACSL1, CREB5) that were relevant to COVID-19-related IS." (PMID 37606960, 2023).
diabetes (2 papers, 2020 to 2023). "To investigate the functional role of increased FXR and CREB5 in PCT cell injury in diabetes, we performed a study in cultured HK2 cells, a cell line derived from human proximal tubular cells." (PMID 37337149, 2023). "Our results suggest that diabetes does not interfere in the transcription of the cAMP responsive element binding protein 5, CREB5, in SMG, and LPLI did not change its mRNA levels expression, means of 1.20 ± 0.34, 2.44 ± 1.00 and 2.01 ± 0.79 for C0, D0 and D20, respectively." (PMID 32750068, 2020).
head and neck squamous cell carcinoma (2 papers, 2022 to 2023). A squamous cell carcinoma that arises from any of the following anatomic sites: lip and oral cavity, nasal cavity, paranasal sinuses, pharynx, larynx, and salivary glands. "CREB5 inhibits mitochondrial apoptosis by promoting the transcription of TOP1MT in head and neck squamous cell carcinoma." (PMID 37821801, 2023).
liver cancer (2 papers, 2018 to 2025). An epithelial or non-epithelial malignant neoplasm that arises from the liver. "Analyses of TCGA datasets and tissue arrays showed that CREB5 mRNA and protein expression levels were higher in liver cancer tissues than in paired normal tissues." (PMID 39915455, 2025). "CREB5 directly bound to the tenascin-C (TNC) promoter to induce EMT in liver cancer cells, which ultimately enhanced invasion and metastasis." (PMID 39915455, 2025). "Further, we knocked down or overexpressed CREB5 in a mouse liver cancer cell line Hep1-6 and found that CREB5 promoted EMT and increased the expression of MMP2 and MMP9 in Hep1-6 cells." (PMID 39915455, 2025). "In summary, our findings suggest that ERS activation promotes EMT in liver cancer cells via SE-mediated upregulation of the CREB5/TNC pathway." (PMID 39915455, 2025). "To further explore the effect of CREB5 on the development of HCC, we analyzed CREB5 expression in several liver cancer cell lines using western blotting and RT-qPCR." (PMID 39915455, 2025). "Given that CREB5 is a transcription factor that regulates TNC in liver cancer cells, we performed a dual-luciferase reporter assay to investigate whether CREB5 increases TNC promoter activity." (PMID 39915455, 2025). "Furthermore, we collected eight pairs of freshly resected liver cancer tissues and adjacent liver tissues for western blotting of CREB5, which showed significantly higher CREB5 expression in HCC tissues than in adjacent normal liver tissues." (PMID 39915455, 2025). "Knockdown of TNC inhibited CREB5-induced promotion of liver cancer cell migration, invasion, and EMT, which further indicated that CREB5 plays a role in promoting EMT through TNC." (PMID 39915455, 2025). "In the human liver cancer cell lines Hep3B and LM3, knockdown of CREB5 increased the expression of the epithelial marker E-cadherin but decreased that of the mesenchymal markers N-cadherin and vimentin, as well as the EMT transcription factor Snail." (PMID 39915455, 2025). "Although this study identified that CREB5, targeted by ERS-related SE, promotes EMT in liver cancer cells by directly activating the transcription of TNC, several questions remain." (PMID 39915455, 2025). "Mechanistically, CREB5 upregulates the transcription of tenascin-C (TNC) by directly binding to its promoter region, thereby promoting EMT in liver cancer cells." (PMID 39915455, 2025). "Moreover, dual-luciferase and ChIP-qPCR assays verified that CREB5 binds to the TNC promoter, promotes transcription of TNC, and plays a role in inducing EMT in liver cancer cells." (PMID 39915455, 2025).
lung carcinoma (2 papers, 2021 to 2022). "It is noted that incidence and death rate in lung cancer is lowest in the Hispanic-American ethnic group, which could be due to a higher frequency of negative effect alleles of SNPs of CREB5 gene in this ethnic group." (PMID 34143809, 2021).
lymph node metastasis (2 papers, 2020 to 2025). "In addition, CREB5 expression levels were significantly correlated with the T classification, lymph node metastasis, and distant metastasis (p < 0.001)." (PMID 32843066, 2020).